GPHRA (golgi pH regulator A)
Description:
Voltage-gated channel that enables the transfer of monoatomic anions such as iodide, chloride, bromide and fluoride which may function in counter-ion conductance and participates in Golgi acidification. Plays a role in lymphocyte development, probably by acting as a RABL3 effector in hematopoietic cells (By similarity). Essential for maintaining the acidic luminal pH of the Golgi apparatus in neurons, which is important for preserving Golgi structural integrity (By similarity). This integrity supports proper axonal transport and synaptic maintenance in cerebellar inhibitory neurons, including Purkinje and basket cells (By similarity). Additionally, Golgi acidification facilitates the activation of SREBP2, thereby ensuring sufficient cholesterol biosynthesis necessary for normal neuronal morphology and function (By similarity).
Synonyms: GPR89; GPR89A; SH120; GPHR; UNQ192
Tractability: Antibody: UniProt predicts a signal peptide or a membrane-spanning region. PROTAC: ubiquitination databases record sites on it; its protein half-life has been measured.
Gene: Protein-coding gene on chromosome 1 (145,607,982 to 145,670,980, forward strand). Ensembl gene ENSG00000117262.
Subcellular location: Golgi apparatus membrane
Subcellular location (Human Protein Atlas): Endoplasmic reticulum
Gene Ontology:
Molecular function: voltage-gated monoatomic anion channel activity
Biological process: intracellular pH reduction; positive regulation of canonical NF-kappaB signal transduction; cholesterol homeostasis; T cell differentiation; monoatomic anion transmembrane transport
Cellular component: Golgi cisterna membrane; Golgi membrane; Golgi-associated vesicle membrane; membrane
Genetic constraint (gnomAD): Loss-of-function variants: 10 observed, 20.01 expected, observed/expected ratio (o/e) 0.5, 90% interval 0.31 to 0.85. The upper end of that interval is the gene's LOEUF score, 0.85, which puts it in group 3 of 6, group 1 being the genes least tolerant of losing a copy. Missense variants: 77 observed, 161.56 expected, observed/expected ratio (o/e) 0.48, 90% interval 0.4 to 0.58. Synonymous variants: 37 observed, 51.23 expected, observed/expected ratio (o/e) 0.72, 90% interval 0.56 to 0.95.
Homologues: Orthologues: chimpanzee GPR89A (100% identical), macaque GPR89A (99% identical), dog GPR89A (98% identical), mouse Gpr89 (97% identical), rat Gpr89b (97% identical), zebrafish GPR89A (90% identical), tropical clawed frog gpr89b (87% identical), Caenorhabditis elegans gphr-1 (56% identical), Drosophila melanogaster GPHR (56% identical), Caenorhabditis elegans gphr-2 (54% identical). Paralogues in human: GPHRB (100% identical).
Diseases named in the same sentence as GPHRA in open-access papers:
GPHRA is named in the same sentence as 11 diseases in open-access papers, as found by Europe PMC text mining. Sharing a sentence is not in itself a finding about the gene and the disease.
GPHRA shares sentences with these, for which no sentence is quoted: cancer (3 papers); breast carcinoma (1); cervical squamous cell carcinoma (1); cholangiocarcinoma (1); endocervical adenocarcinoma (1); infection (1); lung carcinoma (1); papillary adenocarcinoma (1); prostate carcinoma (1); trigonocephaly (1); tumour (1).